LEP (leptin)
Diseases named in the same sentence as LEP in open-access papers (continued):
Sharing a sentence is not in itself a finding about the gene and the disease.
inflammatory bowel disease (16 papers, 2007 to 2025). A spectrum of small and large bowel inflammatory diseases of unknown etiology. "Higher circulating concentration of leptin, a proinflammatory molecule, is associated with many autoimmune and inflammatory diseases, such as inflammatory bowel disease." (PMID 23285260, 2012). "Multiple studies have demonstrated the role of both bacterial species in gastrointestinal diseases, such as inflammatory bowel disease and Crohn’s disease, with the former also involved in the glucose metabolism impairment and positively associated with leptin levels." (PMID 38980850, 2024). "This includes increased urinary adiponectin, lipocalin-2, leptin and interleukin-6 (IL-6) levels in renal diseases and an association of elevated urinary chemerin as well as urinary and fecal lipocalin-2 levels with active inflammatory bowel diseases." (PMID 37189804, 2023). "Previous studies have demonstrated that leptin deficiency as well as the pharmacologic blockade of the leptin receptor attenuate disease severity in mouse models of colitis, highlighting a potential role for leptin in inflammatory bowel diseases." (PMID 31822667, 2019). "The expression of leptin and leptin receptor (Ob-R) has been partially elucidated in colon of patients with inflammatory bowel diseases (IBDs), even though leptin is involved in angiogenesis and inflammation." (PMID 33159578, 2021). "Leptin is considered a proinflammatory adipokine, and plasma levels are increased in inflammatory bowel disease, while adiponectin is considered anti-inflammatory and regulated negatively in intestinal inflammation." (PMID 33537270, 2020). "Leptin concentrations are increased in animals with intestinal inflammation and humans with inflammatory bowel diseases." (PMID 24740401, 2014). "Similar profile of serum adipokine concentrations that is elevated Acrp30 and resistin, and decreased leptin was reported in patients with inflammatory bowel disease." (PMID 24259947, 2013).
knee osteoarthritis (16 papers, 2010 to 2024). "In pain associated with knee osteoarthritis, leptin secreted in the infrapatellar (Hoffa’s) fat can contribute to nociception." (PMID 28226002, 2017). "At the final time point, leptin concentrations were independently associated with a high-fat diet, body fat, and knee osteoarthritis levels." (PMID 20604941, 2010). "Controlling for the effects of diet and percentage body fat with a multivariate model revealed a significant association between knee osteoarthritis severity and serum levels of leptin, adiponectin, and IL-1α." (PMID 20604941, 2010). "Of these changes, systemic leptin, adiponectin, and IL-1α levels remain significantly associated with knee osteoarthritis severity when statistically controlling for the effects of diet and adiposity." (PMID 20604941, 2010). "After controlling for interactions among these variables with a multivariate model, leptin remained significantly associated with percentage body fat and the knee osteoarthritis score." (PMID 20604941, 2010). "For example, higher IL6 were reported in both the synovial fluid and serum of patients with hip osteoarthritis, whereas serum leptin levels have been reported to be higher in patients with knee osteoarthritis." (PMID 29225423, 2017). "Kellgren-Lawrence grade, physical exercise, all anthropometric measurements (especially waist circumference), tumor necrosis factor α, and high levels of leptin, resistin, and ostepontin were related to knee osteoarthritis severity." (PMID 27629533, 2016). "Additionally, the leptin levels were associated with the radiographic progression of cartilage damage, with higher plasma leptin levels found in patients at the more advanced third and fourth radiographic stages of knee osteoarthritis." (PMID 39409194, 2024). "In addition to the endocrinologic problems, leptin also affects the disease processes of various musculoskeletal diseases, such as knee osteoarthritis." (PMID 36295022, 2022). "Authors hypothesized that joint inflammation in knee osteoarthritis may induce an increase in leptin concentrations and, secondarily, catabolic factors such as adipsin, leading to cartilage degradation and loss." (PMID 29483883, 2018). "Despite minimal effects of a high-fat diet on proinflammatory cytokine levels, statistically controlling for the effect of diet and percentage body fat revealed that systemic concentrations of leptin, adiponectin, and IL-1α are predictive of knee osteoarthritis severity." (PMID 20604941, 2010). "Mice lacking production of functional leptin or lacking functional leptin receptors develop extreme obese phenotypes without increased incidence of knee osteoarthritis which suggest that weight alone may not be a risk factor for joint degeneration." (PMID 28250578, 2017). "Leptin tends to increase the levels of C-reactive protein (CRP) and may have a role in maintaining neuropathic pain and pain related to knee osteoarthritis." (PMID 28226002, 2017). "In patients with knee osteoarthritis assessed before and after bariatric surgery, the surgery led to a significant decrease in BMI (20%) with improvement in pain standards and knee function, and a reduction in levels of markers of articular destruction, serum IL-6, CPR, and leptin." (PMID 28226002, 2017).
lung fibrosis (16 papers, 2011 to 2025). "The published studies showed that the inflammatory cytokines of GDF-15 and leptin were associated with infections, metabolism, and lung fibrosis." (PMID 35784345, 2022). "In other diseases associated with extended fibrous tissue production, such as idiopathic pulmonary fibrosis, it was reported that measuring adiponectin/leptin ratio is useful to assess the course of the disease and helps to predict the intensity of fibrosis." (PMID 30806766, 2019). "Leptin treatment can inhibit the activation of mTOR in the progression of pulmonary fibrosis, and mTOR is an important inhibitor of autophagy upstream." (PMID 31700697, 2019). "In fact, leptin is highly deposited in the lung tissues of idiopathic pulmonary fibrosis and is positively correlated with the high-resolution computed tomography (HRCT) scores of patients." (PMID 30832310, 2019). "In conclusion, we identified high concentrations of activated T-cell and B-cell subpopulations associated with altered leptin and cytokine levels in peripheral blood from cohorts with FPF or HPS pulmonary fibrosis." (PMID 29445374, 2018). "Our findings of high peripheral blood concentrations of activated T-cell and B-cell subpopulations and leptin in our cohort with pulmonary fibrosis are interesting." (PMID 29445374, 2018). "Also, leptin signaling is necessary for bleomycin-induced lung fibrosis through a mechanism of peroxisome proliferator-activated receptor gamma (PPARγ) inhibition, which results in enhanced TGF-β1 signaling." (PMID 35610699, 2022). "The lack of significant changes in HDM-induced lung inflammation, together with increased markers of fibrosis, indicates that lung fibrosis may contribute to the observed leptin-induced changes in lung resistance." (PMID 35610699, 2022). "However, in the lung tissue leptin promotes pulmonary fibrosis development by inhibiting autophagy via PI3 K/Akt/mTOR pathway." (PMID 31700697, 2019). "Leptin promotes pulmonary fibrosis also by inhibiting autophagy via PI3K/Akt/mTOR pathway." (PMID 30806766, 2019). "Suggestions that leptin could play a key role in lung fibrosis include that it augments TGF-β1 signaling in lung fibroblasts; it does so by inhibiting PPARγ." (PMID 27642238, 2016). "For example, leptin-resistant mice are protected from bleomycin-induced pulmonary fibrosis." (PMID 27642238, 2016). "The absence of a stronger cellular inflammatory response in CA and HF mice, despite an increased BAL Leptin content, represents an interesting finding, since Leptin resistance was shown to reduce hyperoxia-induced lung inflammation and to protect from lung fibrosis." (PMID 21951864, 2011). "In addition, leptin signaling is required for bleomycin-induced lung fibrosis." (PMID 27642238, 2016). "It is noteworthy that leptin is a proinflammatory cytokine and plays an important role in the pathogenesis of ARDS, liver, and lung fibrosis." (PMID 29436483, 2018). "Leptin is a proinflammatory cytokine and plays an important role in the pathogenesis of ARDS, liver, and lung fibrosis." (PMID 27642238, 2016). "Serum concentrations of leptin were significantly higher in patients with HPS pulmonary fibrosis with or without patients with FPF compared with URels." (PMID 29445374, 2018). "Earlier studies have found that LEP can be used as a marker molecule based on inflammation in COPD patients, and the negative correlation between LEP and pulmonary fibrosis has also been demonstrated." (PMID 40337271, 2025).
mental disorder (16 papers, 2015 to 2026). A disease that has its basis in the disruption of mental process. "Patients with major psychiatric disorders had significant lower ReHo in primary sensory and visual association cortices and higher ReHo in the frontal cortex and angular gyrus; plasma leptin levels were also elevated." (PMID 32699219, 2020). "The relationship between leptin levels and psychiatric disorders has been studied more extensively in adults than in children and adolescents." (PMID 41489631, 2026). "Leptin was at a high level in the early stage of mental illness or in the late stage of treatment, and was closely related to the high incidence of abnormal blood lipid metabolism." (PMID 36090349, 2022). "More recently, the influence of metabolic stressors on leptin secretion has become an important focus of research on feeding behaviors and mental disorders." (PMID 34884416, 2021). "In a dimensional transdiagnostic approach, we examined depressive symptoms and their relationships with regional homogeneity and leptin across major psychiatric disorders." (PMID 32699219, 2020). "Among these markers, leptin, an adipocyte hormone, has recently received significant interest in psychiatric disorders." (PMID 27610173, 2016). "In recent years, leptin, an adipocyte hormone, has gained significant interest in psychiatric disorders." (PMID 27610173, 2016). "Absolute leptin levels differed between psychiatric disorders (p < .001)." (PMID 41489631, 2026). "Variations in leptin levels secreted by adipocytes can affect appetite regulation and energy metabolism, potentially leading to cognitive dysfunction in individuals with severe mental illnesses due to fluctuations in leptin levels." (PMID 39911400, 2025). "Although the regulatory actions of leptin on energetics and food intake have been extensively reported, emerging data support its importance in neural development and plasticity, hippocampal function, and psychiatric disorders, including PTSD." (PMID 27844058, 2016). "Gut-brain hormones, including leptin, may influence the perception of mental illness severity." (PMID 39911400, 2025). "According to current existing literature, elevated serum leptin levels in psychiatric patients treated by antipsychotics, mainly SGAs, tend to be recognized as the consequence of the underlying mental disorders and/or antipsychotics induced weight gain, but not to be the cause of body weight gain." (PMID 32033608, 2020). "The associations reported here between psychiatric disease, leptin physiology, and poor fetal growth do not necessarily reflect causal relationships, but determining the underlying factors that link them should help to identify modifiable causes of poor fetal growth." (PMID 26303856, 2015). "In older persons without major neurological or psychiatric disorders, serum leptin was inversely correlated with executive function." (PMID 39822062, 2025). "While global tests suggested differences in leptin z-scores between patients with different psychiatric disorders, these differences could not be attributed to diagnosis groups in post-hoc pairwise comparisons." (PMID 41489631, 2026).
myeloma (16 papers, 2015 to 2025). "Despite the comprehensive exploration of leptin’s role in the development of MM, a striking deficiency remains in our knowledge regarding myeloma-related bone disease." (PMID 40565082, 2025). "In myeloma-associated bone disease, reprogrammed adipocytes increase leptin secretion while decrease adiponectin secretion to intensify osteoclastogenesis and to retard osteoblastogenesis, which is consistent with our pooled results." (PMID 35073877, 2022). "An epidemiologic study showed that low adiponectin and high leptin levels are associated with an increased tumour risk in multiple myeloma." (PMID 31334678, 2019). "When co-culturing with adipocytes, the proliferation of myeloma cells was increased and the anti-tumor efficacy of chemotherapy drugs was reduced, associated with up-regulation of cell cycle and anti-apoptosis proteins via leptin." (PMID 27863383, 2016). "Bone marrow adipocytes have been implicated in the early phases of proliferation in multiple myeloma possibly through leptin secretion and may play a role in the growth of ALL blasts." (PMID 25962143, 2015). "Adipokines, such as leptin and IL-6, induce myeloma cell survival and proliferation, but targeting adipokines in MM or cancer generally has not had great translational success and new targets, based on a better understanding of the pathology, are needed." (PMID 36909335, 2023). "BM adipocytes secrete several adipokines and growth factors (e.g., MCP-1, SDF-1α, leptin, TNFα, insulin, resistin) which recruit myeloma cells and promote myeloma growth and protection from chemotherapy." (PMID 34067236, 2021). "Co-culture experiments have also demonstrated that BMAd-derived leptin supports survival of myeloma cells during chemotherapy treatment, and that autophagy activation within myeloma tumor cells is one mechanism of this survival." (PMID 32124181, 2020). "Adipocyte-derived factors such as MCP-1/CCL2 and SDF1α/CXCL12 are chemotactic factors for myeloma cells, while other adipokines promote myeloma proliferation (e.g., leptin/LEP) and resistance to chemotherapies (e.g., leptin/LEP, adipsin/CFD)." (PMID 33680918, 2020). "In vitro, myeloma cells co-cultured with adipocytes showed enhanced proliferation and migration, and leptin was found to clearly play a role in this process." (PMID 31334678, 2019). "This study aims to explore the effect of leptin on development and chemoresistance in multiple myeloma cells and the potential mechanism." (PMID 27863383, 2016). "In order to well understand how leptin exert its role in promoting cancer, we treated myeloma cells with recombinant leptin at several concentrations and times." (PMID 27863383, 2016). "We used 3T3-L1 differentiated mature adipocytes to study the impact of leptin on the biological behaviors of multiple myeloma cells." (PMID 27863383, 2016). "We have identified that the level of leptin is increased and adiponectin is decreased in newly diagnosed myeloma compared to healthy controls." (PMID 27863383, 2016). "Few studies have investigated the effects of leptin in hematological tumors and found that leptin modestly promotes proliferation of myeloma cell lines, and reduces chemotherapy induced apoptosis in myeloma cell lines, which are in accordance with our results." (PMID 27863383, 2016). "Leptin also appears have proliferative and anti-apoptotic effects in myeloma cells." (PMID 36909335, 2023). "Analysis of levels of adipokines including leptin and adiponectin in 28 multiple myeloma patients identified significantly higher leptin compared with 28 normal controls(P < 0.05), and leptin level was positively correlated with clinical stage, IgG, ER, and ß2MG." (PMID 27863383, 2016). "As leptin level was significantly increased in myeloma patients, we tried to determine whether the pro-proliferation effect of adipocytes was through leptin or not." (PMID 27863383, 2016).
myeloma (continued). "Our study demonstrate that up-regulated leptin could stimulate proliferation and reduce the anti-tumor effect of chemotherapy in multiple myeloma possibly via activating AKT and STAT3 pathways, and leptin might be one of the potential therapeutic targets for treating myeloma." (PMID 27863383, 2016). "In addition, Leptin was correlated with ISS stage in patients with multiple myeloma." (PMID 27863383, 2016). "By using AG490, an agent blocking the phosphorylation of AKT and ERK, the proliferation of myeloma cells was inhibited, as well as the phosphorylation of AKT and STAT3, even adding leptin." (PMID 27863383, 2016). "Leptin activates the AKT/STAT3 pathway, increases Bcl-2 levels, and suppresses caspase-3 and in turn apoptosis, which collectively contribute to the development of chemo-resistance in myeloma." (PMID 31334678, 2019). "Leptin stimulated the growth of both myeloma cells via increasing AKT and STAT3 phosphorylation, without changing expression of AKT and STAT3." (PMID 27863383, 2016). "We next highlighted the ways in which BMAT may support MM, for example, through bioactive lipids (as a fuel source, signaling molecule, and a substrate for lipid peroxidation), and myeloma-supportive adipokines (e.g., IL-6, TNFα, MCP-1, PAI-1, IL-6, resistin, and leptin)." (PMID 27379019, 2016). "Taken together, our study demonstrated that up-regulated leptin could stimulate proliferation of myeloma and reduce the anti-tumor effect of chemotherapy possibly via activating AKT and STAT3 pathways, and leptin might be one of the potential therapeutic targets for treating myeloma." (PMID 27863383, 2016).